SOWAHB (sosondowah ankyrin repeat domain family member B)
Synonyms: ANKRD56
Tractability: PROTAC: its protein half-life has been measured.
Gene: Protein-coding gene on chromosome 4 (76,894,152 to 76,898,144, reverse strand). Ensembl gene ENSG00000186212.
Subcellular location (Human Protein Atlas): Nucleoli fibrillar center
Gene Ontology:
Molecular function: protein binding
Genetic constraint (gnomAD): Loss-of-function variants: 18 observed, 19.89 expected, observed/expected ratio (o/e) 0.91, 90% interval 0.62 to 1.34. The synonymous counts are far from expectation, so gnomAD's model fits this gene poorly and the ratio says little. Missense variants: 1,126 observed, 978.95 expected, observed/expected ratio (o/e) 1.15, 90% interval 1.09 to 1.21. Synonymous variants: 496 observed, 416.33 expected, observed/expected ratio (o/e) 1.19, 90% interval 1.11 to 1.28.
Homologues: Orthologues: chimpanzee SOWAHB (99% identical), macaque SOWAHB (95% identical), pig SOWAHB (75% identical), rat Sowahb (67% identical), dog SOWAHB (65% identical), mouse Sowahb (65% identical), guinea pig SOWAHB (54% identical). Paralogues in human: SOWAHA (19% identical), SOWAHC (17% identical), SOWAHD (10% identical).
Diseases named in the same sentence as SOWAHB in open-access papers:
SOWAHB is named in the same sentence as 2 diseases in open-access papers, as found by Europe PMC text mining. Sharing a sentence is not in itself a finding about the gene and the disease. The quoted sentences say what the papers report.
renal disease (1 paper, 2021). "By utilizing a custom target NGS 70-gene panel and a validation cohort, we have been able to point out some of these rare variants in the MYH9, CNDP1, SOWAHB and RGMA genes relevant to renal disease in diabetic patients." (PMID 34946941, 2021).
SOWAHB also shares sentences with these, for which no sentence is quoted: Fraser syndrome (1 paper).